HDAC2 (histone deacetylase 2)
Diseases named in the same sentence as HDAC2 in open-access papers (continued):
Sharing a sentence is not in itself a finding about the gene and the disease.
colitis (6 papers, 2018 to 2024). Inflammation of the colon. "Our results also show that CD4+ T cell-specific conditional deletion of HDAC2 exacerbates colitis and EAE, and this is associated with elevated IL-17 expression." (PMID 30375383, 2018). "For example, our previous study showed that the epigenetic modifier Tet2 associates Hdac2 to repress IL-6 during inflammation resolution in myeloid cells, which restrains DSS-induced colitis in mice." (PMID 38346956, 2024). "Mice with conditional deletion of HDAC2 in CD4+ T cells have elevated IL-17 expression and severe colitis." (PMID 30375383, 2018).
COVID-19 (6 papers, 2020 to 2023). A disease caused by infection with severe acute respiratory syndrome coronavirus 2. "HDAC2 and other epigenetic modifiers were predicted as potential regulators of ACE2 from correlation and network analyses of lung transcriptome from COVID-19 patients." (PMID 38162580, 2023). "In this study, we analyzed the expression profile of DNMTs (DNMT1, DNMT3A, DNMT3B) and HDACs (HDAC2 and HDAC3) in COVID-19 patients." (PMID 36840831, 2023). "NICEdrug.ch strategy to fight COVID-19, and NICEdrug.ch candidate inhibitors of SARS-CoV-2 host factors: reverse transcriptase and HDAC2." (PMID 34340747, 2021). "We conducted a case-control study to investigate the differential expression of DNMT1, DNMT3A, DNMT3B, HDAC2, and HDAC3 in the blood of 120 patients (30 mild, 30 moderate, 30 severe, and 30 critical) and 30 healthy subjects without COVID-19." (PMID 36840831, 2023). "In contrast to previous reports, DNMT3A and DNMT3B expression was found to be significantly downregulated in COVID-19 cases, whereas DNMT1, HDAC2, and HDAC3 expression did not change." (PMID 36840831, 2023).
esophageal squamous cell carcinoma (6 papers, 2018 to 2023). Esophageal squamous cell carcinoma (ESCC) is a type of esophageal carcinoma (EC) that can affect any part of the esophagus, but is usually located in the upper or middle third. "The expression level of HDAC2 was higher in esophageal squamous cell carcinoma (ESCC) tissues than in atypical hyperplasia tissues." (PMID 36968022, 2023). "A recent study showed that HDAC2 can bind to miR-503-5p and target CXCL10, thus promoting the progression of esophageal squamous cell carcinoma." (PMID 36189258, 2022). "Although esophageal squamous cell carcinoma (ESCC)-oriented mechanism has been widely explored, the integrated action of histone deacetylase 2 (HDAC2), microRNA (miR)-503-5p and C-X-C motif chemokine 10 (CXCL10) in ESCC has not been thoroughly explored." (PMID 33926524, 2021).
lung disease (6 papers, 2007 to 2023). "HDAC2 can suppress inflammatory gene expression while the activity and expression of HDAC2 were inhibited in peripheral lung and alveolar macrophages with pulmonary diseases, such as COPD." (PMID 35280995, 2022). "Indeed, glucocorticoids (one of the mainstays of therapy for pulmonary diseases) reverses histone acetylation of activated inflammatory genes by binding liganded glucocorticoid receptors to coactivators, by recruiting histone deacetylase-2 to the activated transcription complex." (PMID 17916252, 2007).
lymph node metastasis (6 papers, 2016 to 2024). "In our study, not only lower HDAC-4 but also lower HDAC-2 expression was associated with the presence of lymph node metastasis." (PMID 38790909, 2024). "The expression of HDAC2 was closely associated with histological grade, and lymph node metastasis." (PMID 36968022, 2023). "Interestingly, the presence of lymph node metastasis was associated with lower levels of HDAC-2 expression, which was an association that was stronger in tumors with serous histology (Mann–Whitney U test, p = 0.045) and was of borderline significance in the whole cohort (p = 0.081)." (PMID 38790909, 2024). "Specifically, HDAC-2 overexpression was found to correlate with anthracycline resistance, lymph node metastasis, Ki-67 expression, advanced TNM stage, and higher histological grade in BC." (PMID 36294811, 2022). "The presence of a similar association between HDAC-2 and -4 and lymph node metastasis is interesting, especially since there was not any significant association between HDAC-2 and HDAC-4." (PMID 38790909, 2024). "High levels of HDAC2 were correlated with a high incidence of lymph node metastasis in human gallbladder carcinoma (PGC) and could predict a poor prognosis in patients with cholangiocarcinoma (CCA)." (PMID 36968022, 2023). "HDAC-2 positivity was correlated with the absence of lymph node metastasis in serous tumors (p = 0.045)." (PMID 38790909, 2024). "Meanwhile, HDAC2 was upregulated in HNSCC patients with lymph node metastasis compared to those without lymph node metastasis (p = 0.035)." (PMID 36814797, 2023). "Moreover, it was also reported that most Kcr regulators, including DPF2, KAT2B, and HDAC2–3, were significantly dysregulated in patients with head and neck squamous cell carcinoma (HNSCC); this observation positively correlated with lymph-node metastasis, T stage, and histologic grade." (PMID 38315203, 2024).
osteoarthritis (6 papers, 2018 to 2024). A noninflammatory degenerative joint disease occurring chiefly in older persons, characterized by degeneration of the articular cartilage, hypertrophy of bone at the margins and changes in the synovial membrane. "Upregulation of miR-92a-3p also regulated cartilage development and maintains homeostasis by directly targeting HDAC2 in both MSCs and primary human chondrocytes affected by osteoarthritis." (PMID 38816719, 2024). "Studies have shown that HDAC2 can inhibit cartilage-specific gene expression and induce osteoarthritis." (PMID 36833438, 2023). "The study was preceded by previous findings about miR-92a-3p upregulation in hADSC-derived chondrocytes and chondrogenic hMSCs, as well as osteoarthritis cartilage, where histone deacetylase 2 (HDAC2) was identified as a target gene of miR-92a-3p." (PMID 30717449, 2019). "We have been suggested that exosomes derived from AC‐miR‐95‐5p (AC‐miR‐95‐5p‐Exos) would enhance chondrogenesis and prevent the development of osteoarthritis by directly targeting HDAC2/8." (PMID 30063117, 2018). "Increased expression of HDAC2/8 occurs in the tissues and chondrocyte‐secreted exosomes of patients with osteoarthritis and mediates cartilage‐specific gene expression in chondrocytes." (PMID 30063117, 2018). "Thus, AC‐miR‐95‐5p‐Exos may act as an HDAC2/8 inhibitor and exhibit potential as a disease‐modifying osteoarthritis drug." (PMID 30063117, 2018). "The predicted pathway also correlated the Histone Deacetylase 2 (HDCA2) with IL6 and MMP9 and RELA which was seem to be boost the progression of osteoarthritis by repressing cartilage specific gene." (PMID 29731966, 2018).
pancreatic adenocarcinoma (6 papers, 2009 to 2024). "It is difficult to determine at this stage whether upregulation of HDAC7/HDAC2/Nur77 in pancreatic adenocarcinomas is a cause or a consequence of malignant progression." (PMID 25275504, 2014). "Kaplan-Meier survival curves indicated that pancreatic adenocarcinoma patients presenting concomitant high HDAC-1/HDAC-2 expression had significantly longer survival times compared to those with low expression (log-rank test, p = 0.0255)." (PMID 26502922, 2015). "Kaplan-Meier survival curves indicated that pancreatic adenocarcinoma patients presenting high HDAC-2 expression had marginally longer survival times compared to those with low expression (log-rank test, p = 0.0634)." (PMID 26502922, 2015). "Recent studies demonstrated that HDAC2 was overexpressed in pancreatic adenocarcinoma tissue samples." (PMID 25275504, 2014). "In the present study, by using a new approach we provide evidence that several genes namely HDAC7, HDAC2 and Nur77 are overexpressed in significantly high percentage of pancreatic adenocarcinoma tumors compared to benign tumors and chronic pancreatitis." (PMID 25275504, 2014). "High HDAC-2 expression was noted in 35 (50.0 %) out of 70 pancreatic adenocarcinoma cases." (PMID 26502922, 2015). "Forty-nine (74.2 %) out of 70 pancreatic adenocarcinoma cases were found HDAC-2 positive." (PMID 26502922, 2015). "Forty-seven (69.1 %) out of 70 pancreatic adenocarcinoma cases were found HDAC-2 positive." (PMID 26502922, 2015). "Using the GSE15471 and TCGA-Pancreatic adenocarcinoma (PAAD) datasets, we analyzed the clinical importance of TOP2A-associated genes (HDAC1, HDAC2, HMGB1, HMGB2, NFYA, NFYB, NFYC, and SP1)." (PMID 32977589, 2020). "Pancreatic adenocarcinoma patients with enhanced HDAC-1 and −6 expression showed significantly longer survival times compared to those with low expression (p = 0.0022 and p = 0.0113, respectively), while a borderline association concerning HDAC-2 expression was noted (p = 0.0634)." (PMID 26502922, 2015). "Pancreatic adenocarcinoma displayed strong nuclear immunoreactivity for HDAC1 (32%), HDAC2 (63%), HDAC3 (79%) and RelA/p65 (45%) in a considerable number of cases." (PMID 19912635, 2009). "High HDAC-2 expression was more frequently observed in pancreatic adenocarcinoma patients presenting smaller tumor size, absence of lymph node metastases and earlier histopathological stage, at a non significant level though (p = 0.2046, p = 0.2312 and p = 0.2320, respectively)." (PMID 26502922, 2015).
chronic myeloid leukemia (5 papers, 2012 to 2024). "KEGG pathway analysis revealed that four hub genes- ABL1, HDAC1, HDAC2 and MDM2 - were primarily associated with chronic myeloid leukemia (KEGG:05220 and P = 3.27E-08) and notch signaling pathway (KEGG:04330 and P = 2.38E-04)." (PMID 38832038, 2024). "For instance, using data from K562 cell line, we show the recovery of a large-scale enhancer regulatory network, depending on HDAC2 and GATA1 rescued peaks, whose components are involved in Chronic Myeloid Leukemia (CML) and several cancer-associated processes." (PMID 37286963, 2023).
colorectal tumours (5 papers, 2006 to 2024). "Growing evidence suggests that HDAC2 is elevated in colorectal tumours and is associated with adverse clinical outcomes." (PMID 38804602, 2024). "HDAC2 is frequently elevated in colorectal tumours and associated with tumour progression." (PMID 38804602, 2024). "As expected, we found that human colorectal tumour samples showed higher levels of phospho-Rb and phospho-HDAC2 than the control." (PMID 34911954, 2021). "The increased expression of HDAC2 in colorectal tumors is thought to be mediated by the activation of Wnt/beta-catenin pathway presumably through the activation of c-Myc." (PMID 21346816, 2011). "In our series HDAC2 overexpression was observed in 50% of colorectal tumours compared to their normal pairs." (PMID 16638127, 2006). "5-fluorouracil causes an enrichment of HDAC2-negative RKO cells in vitro and in a subset of primary colorectal tumors in mice." (PMID 35608750, 2023).
endometriosis (5 papers, 2018 to 2024). The growth of functional endometrial tissue in anatomic sites outside the uterine body. "For example, the depletion of histone deacetylase 2, HDAC2, can significantly promote the apoptosis of endometriosis cells." (PMID 38397379, 2024). "In order to explore the effect of the HDAC2/HNF4A axis on endometriosis cells, HDAC2 and HNF4A were silenced in the endometriosis cell line hEM15A alone or in combination." (PMID 34586697, 2021). "HDAC2 silencing reduced the area and weight of endometriosis tissues, suppressed endometriosis cell proliferation and accelerated endometriosis cell apoptosis." (PMID 34586697, 2021). "In order to explore the effect of HDAC2 on endometriosis in vivo, the mouse model of endometriosis was established." (PMID 34586697, 2021). "In order to explore the effect of HDAC2 on endometriosis cells, HDAC2 was silenced in endometriosis cell line hEM15A." (PMID 34586697, 2021). "Western blot analysis and immunohistochemistry described that the protein expression of HDAC2 in endometriosis tissues was significantly higher than that in normal tissues." (PMID 34586697, 2021). "Immunohistochemistry and TUNEL staining manifested that compared with the sh‐NC group, Ki‐67 protein expression in the sh‐HDAC2 group was conspicuously declined in endometriosis tissues, and the apoptosis rate was evidently elevated." (PMID 34586697, 2021). "The results showed that compared with the sh‐NC group, endometriosis mice in the sh‐HDAC2 group had distinct reduction of the area and weight of endometriosis tissues." (PMID 34586697, 2021). "Taken together, silencing HDAC2 repressed the proliferation and invasion and induced the apoptosis of endometriosis cells." (PMID 34586697, 2021). "The microarray‐based analysis in our study indicated that upregulated HDAC2 was a key gene for endometriosis, and tissue experiments confirmed the upregulation of HDAC2 in endometriosis tissues." (PMID 34586697, 2021). "Further ChIP analysis documented that HDAC2 increased significantly in the promoter region of HNF4A in endometriosis tissues compared with normal tissues." (PMID 34586697, 2021). "Collectively, silencing HDAC2 could repress the proliferation and invasion and augmented the apoptosis of endometriosis cells by upregulating HNF4A." (PMID 34586697, 2021). "Thus, our study was designed to explore the role of HDAC2 in endometriosis and the related specific mechanism." (PMID 34586697, 2021). "Notably, the data in our research also exhibited that HDAC2 silencing repressed cell proliferation and invasion but accelerated cell apoptosis in endometriosis cell line hEM15A." (PMID 34586697, 2021). "Therefore, this study was designed to explore the mechanism of HDAC2 orchestrating hepatocyte nuclear factor 4α/AT‐rich interactive domain 1A (HNF4A/ARID1A) axis in endometriosis." (PMID 34586697, 2021). "Moreover, the involvement of histone deacetylase 2 (HDAC2) has been identified in endometriosis." (PMID 34586697, 2021). "Furthermore, a prior study has elucidated the upregulation of HDAC2 in endometriosis." (PMID 34586697, 2021). "HDAC1, HDAC2, HDAC3, Sirtuin 1, and Sirtuin 3, are the five most studied HDAC enzymes which seem to, at least partly, influence the pathophysiology of endometriosis." (PMID 37174627, 2023). "In order to explore the effect of HDAC2 on endometriosis, HDAC2 expression data were extracted from GSE37837 to draw the box plot, which revealed HDAC2 high expression in endometriosis." (PMID 34586697, 2021). "The results of phenolyzer analysis showed that ITGB1, HDAC2 and LAMB1 were the top three important genes in endometriosis." (PMID 34586697, 2021). "A study investigating HDAC expression of endometriosis showed that levels of gene and protein expressions of HDAC1 and HDAC2 were higher in ectopic endometrium than in normal endometrium." (PMID 29780815, 2018).
endometriosis (continued). "In this context, we speculated that the network of HDAC2, HNF4A and ARID1A might be correlated with the pathogenesis of endometriosis." (PMID 34586697, 2021). "Consequently, our data unravelled that silencing HDAC2 increased HNF4A expression through inhibition of deacetylation to upregulate ARID1A, thus preventing endometriosis." (PMID 34586697, 2021). "Collectively, HDAC2 silencing might upregulate HNF4A via repression of deacetylation to activate ARID1A, thus preventing the occurrence of endometriosis." (PMID 34586697, 2021). "HDAC2 was upregulated but HNF4A and ARID1A were downregulated in endometriosis tissues." (PMID 34586697, 2021). "In order to explore the effect of HDAC2 on the expression of HNF4A during endometriosis, we first found a significant negative correlation between HDAC2 and HNF4A expression in endometriosis by GSE37837." (PMID 34586697, 2021).
epilepsy (5 papers, 2015 to 2024). A brain disorder characterized by episodes of abnormally increased neuronal discharge resulting in transient episodes of sensory or motor neurological dysfunction, or psychic dysfunction. "As a widely-known HDAC2 inhibitor, VPA is proved to be safe for treating central nervous system diseases such as epilepsy as well as cancer and it has been in use for more than 50 years." (PMID 34674775, 2021). "HDAC2—the target of the antiepileptic drug Valproate—is overexpressed in the brain of TLE patients and its transcriptional repression activity plays an important role in the pathogenesis of epilepsy." (PMID 26011637, 2015).
nasopharyngeal carcinoma (5 papers, 2013 to 2025). A carcinoma arising from the nasopharyngeal epithelium. "In nasopharyngeal carcinoma, HDAC2 was shown to enhance ACSL4 acetylation, thereby promoting ferroptosis and radiosensitivity." (PMID 40947430, 2025). "Inhibition of c-Abl may be a pharmacological strategy for preventing the adverse effects of elevated HDAC2 levels in nasopharyngeal carcinoma patients." (PMID 36313229, 2022). "Moreover, upregulated EZH2 formed a co-repressor complex with HDAC1/HDAC2/Snail to inhibit E-cadherin which was responsible for the aggressiveness, invasion and metastasis of nasopharyngeal carcinoma cell." (PMID 24345883, 2013).
schizophrenia (5 papers, 2020 to 2023). A major psychotic disorder characterized by abnormalities in the perception or expression of reality. "Moreover, HDAC2 (Ser394) phosphorylation disinhibits oxidative stress-induced neuroapoptosis and may thereby contribute to the aberrant neuroinflammatory and neurodegenerative processes implicated in the pathophysiology of ADHD, autism, and schizophrenia." (PMID 32138755, 2020). "Of additional pertinence to neurodevelopmental disorders and the multigenerational impacts of DNE, phospho-HDAC2 (Ser394) derepresses oxidative neuroinflammation and neuroapoptosis and may thereby contribute to the pathophysiology of ADHD, autism, and schizophrenia." (PMID 32138755, 2020).
acute kidney injury (4 papers, 2016 to 2025). Sudden and sustained deterioration of the kidney function characterized by decreased glomerular filtration rate, increased serum creatinine or oliguria. "Results from this study also implicated that targeting HDAC2 might be a specific therapeutic approach for the treatment of progressive acute kidney injury." (PMID 27145860, 2016). "Furthermore, miR-223-3p in extracellular vesicles of human medulla ossium mesenchymal stem cells alleviate inflammation and pyroptosis in acute kidney injury (AKI) by targeting HDAC2 and enhancing SNRK transcription." (PMID 40372489, 2025).
autism (4 papers, 2020 to 2025). Persistent deficits in social interaction and communication and interaction as well as a markedly restricted repertoire of activity and interest as well as repetitive patterns of behavior. "The inhibitory action of the plant extract compounds on HDAC2, as mentioned in silico, would be a probable antioxidant pathway to limit oxidative neuronal damage linked to the autism spectrum." (PMID 40079500, 2025). "Molecular docking studies demonstrated that P. africanum compounds can interact with HDAC2 and H3R in the autism spectrum." (PMID 40079500, 2025). "To identify potential epigenetic aberrations in the VPA-induced autism model, we examined the levels of class I HDACs (HDAC1, HDAC2, HDAC3, and HDAC8) and AcH3 in the PFC nuclear fraction." (PMID 33994921, 2021).